CD4 (CD4 molecule)
Diseases named in the same sentence as CD4 in open-access papers (continued):
Sharing a sentence is not in itself a finding about the gene and the disease.
tumor (continued). "We have also reported that tumor-reactive CD8+ T cells produce CXCL13, and the frequency of those cells among the DP CD8+ cells positively correlated with the frequency of CXCL13+ DP CD4+ cells in both HNSCC and CRC." (PMID 35439168, 2022). "By contrast, no change was seen in the proliferation of tumor-infiltrating NK cells or Tregs, and the proliferation of FoxP3- CD4+ T cells increased in βA-secreting tumors." (PMID 35580932, 2022). "The results were coincident with above that activated NK cells, gamma delta T cells, plasma cells, naive B cells, activated CD4 memory T cells, and CD8 T cells were more likely to infiltrate in m6A cluster B, which also suggested that cluster A and B had a better anti-tumor immune response." (PMID 36105819, 2022). "In addition, OPRL1 can activate markers on the surface of T cells, enhance CD4+ T and CD8+ T-cell proliferation, and alter cytokine secretion, which is closely involved in tumor progression." (PMID 36011316, 2022). "This therapeutic outcome was due to increased tumor infiltration of CD4+ and CD8+ T cells, but not Tregs." (PMID 36091031, 2022). "Abundant accumulation of Tregs in tumor tissues may be due to the recruitment of Tregs from other parts of the body to the tumor area by chemokines and/or proliferation/differentiation of CD4+CD25+ Tregs from peripheral CD4+CD25− T cells." (PMID 35935577, 2022). "On the other hand, even in the absence of CD8+ T cells, CD4+ T cells also directly kill tumour cells through an IFN-γ-dependent mechanism." (PMID 34731284, 2022). "Tumor-infiltrating T cells are populations containing many different subsets of cells, which can be divided into different subsets according to different differentiated antigens, including five types, namely, CD3+, CD4+, CD8+, CD16+, and CD25+." (PMID 36124030, 2022). "By reducing levels of Treg cells, CD4 CARs may avoid this immunosuppression, which could lead to more profound CAR T cell expansion and anti-tumor activity." (PMID 36172388, 2022). "On the 3rd day after treatment with the DC-based vaccine, no changes in the percentage of CD4+ in the tumor tissue collected from the experimental mice were observed." (PMID 35372586, 2022). "Interestingly, we found that T-cell clusters were present at high levels in immune cells, and the presence of infiltrating T cells in tumor tissues was confirmed using immunohistochemistry (IHC) with CD3E, CD4 and CD8 antibodies." (PMID 36466840, 2022). "CD4+ Tconv cells produced more IFN-γ in the tumor compared with matched peripheral blood independent of pretreatment but showed enhanced IL-2 production in the NEO cohort compared with the PR cohort." (PMID 36509285, 2022). "A multicolor flow cytometry assay was used to identify and assess the frequency of tumor-infiltrating (TILs) immune cells (e.g., CD3 [T cells], CD8 [T cells], CD4 [helper T cells], CD11b [dendritic cells], CD206 and I-A/I-E [F4/80 macrophages], CD335 [NK cells])." (PMID 36457491, 2022). "A similar analysis of CD45+ immune cells from the draining lymph nodes near the tumor also showed that the population of CD8+ T cells but not CD4+ T cells were much more in the SENP3–9A tumor model than in the SENP3-WT tumor model." (PMID 35869062, 2022). "Given that M1-type macrophage, and CD4+ and CD8+ T cells, exert antitumor effects, these results suggest that IFN-γ enhanced St.∆ppGpp-priming of this immune cell response, leading to further tumor suppression." (PMID 36246355, 2022). "Alterations of tumor characteristics matched our other models except for a lack of change in CD4+ T cell recruitment." (PMID 35626096, 2022).
tumor (continued). "On the other hand, the absence of CD3+ T cells in the spleen and the absence of LNs containing CD3+ T cells in the recipient mice transplanted with CARD11(E626K)CD4-Cre and HBZ Tg CD4+ T cells indicate that they developed inflammation, but not neoplasm." (PMID 36446869, 2022). "When the immunophenotypes of the tumor samples were compared with the blood samples, statistically significant differences in the incidences of the CD3+ CD69+, CD4+ CD69+, and CD8+ CD69+ T cells in the tumor samples were 7.83, 9.67, and 10.5 times higher, respectively." (PMID 35158748, 2022). "Co-culture of tumor cells with CD4 + CD25 + CD127dim Treg led to functional changes: enhanced invasion, migration and viability indicated that increased levels of Treg in the tumor microenvironment may promote tumor growth." (PMID 36098901, 2022). "Notably, the ratio of Treg populations in B7x+ MC38 tumors was elevated in comparison to the Foxp3− conventional CD4+ T cell and CD8+ T cell populations, indicating that B7x was shifting the immune landscape of the tumor to a more suppressive milieu." (PMID 35523809, 2022). "The infiltration of CD8+T cells, CD4+T cells, and FOXP3+Tregs were detected in tumours." (PMID 36195696, 2022). "Results indicated that the expression of Tumor-related SHC1 was significantly correlated with the tumor-infiltration of CD8+ T cells, CD4+ T cells, B cells, neutrophils, macrophages, and myeloid dendritic cells in 19, 12, 16, 20, 18, and 17 cancers, respectively." (PMID 35601500, 2022). "The 4 markers CD4, CD8, CD68, and MMP9 were compared to the different prognostic markers aimed at detecting any effect of these immune marker expressions on the prognosis of the tumor." (PMID 35083113, 2022). "We found that GINS1 expression was positive correlated with tumor purity (r = 0.338, p = 5.94e-08), and negative correlated with the levels of tumor-infiltrating CD4+ T cell (r = −0.234, p = 2.56e-04) and macrophages (r = −0.233, p = 3.21e-04)." (PMID 36092720, 2022). "It is well known that CD4+ T cell populations are abundant in this environment, including pro-tumor CD4+ regulatory T cells (Tregs) and anti-tumor Th1 cells, but the role of Th2 cells is not clear so far." (PMID 35664314, 2022). "In addition, the polyclonal tumor-reactive CD4+T cells also showed certain effect on the metastasis control, which give further evidence for the use of CD4+T cell ACT for tumor immunotherapy." (PMID 35784297, 2022). "Specifically, a high-dose of vitamin C increased the infiltration of CD4+ and CD8+ T cells and macrophages into TME, increased the production of granzyme B by CD8+ T cells and interleukin-12 by macrophages, and suppressed tumor growth in a T cell–dependent manner." (PMID 35330159, 2022). "This was insufficient to meet predefined threshold criteria for efficacy, although the limited number of paired tumor biopsies examined did demonstrate the expected bioactivity, including a reduction in CSF1-dependent CD16-expressing monocytes, and increased CD4+ and CD8+ T cell numbers." (PMID 36077755, 2022). "Then, to examine the type(s) of T cell clones that were expanded by co-culture with tumor cells, we sorted PD-1-expressing (or not expressing) CD4+ or CD8+ T cells from non-metastatic lymph nodes and compared their clonotypes with those of TILs in case C207." (PMID 35606862, 2022). "Furthermore, ANOVA tests on the tumor‐enriched clusters revealed that CD8‐c09‐Isg15, CD8‐c10‐Cd244, CD8‐c11‐Ccr7, CD8‐c12‐Gzmc, CD4‐c09‐Gzmb, Macro‐c03‐Ifit3, and NK‐c03‐Ccl5 were impacted by combined effects of liver tumors and anti‐PD‐1 treatment." (PMID 36911291, 2022). "abundance correlated with higher levels of tumor-infiltrating CD8+ T cells and effector CD4+ and CD8+ T cells in the systemic circulation and peripheral cytokines that promoted a response to anti-PD-1 therapy, and these markers were inverse in those with Bacteroidota abundance." (PMID 36358789, 2022).
tumor (continued). "However, there is mounting evidence in support of cytotoxic CD4+ T cells as potential anti-tumor agents, involved in MHC-II-mediated tumor killing." (PMID 35223828, 2022). "Representative immune markers were used to describe the infiltration levels of immune cells in the tumor microenvironment, for example, CD4+ T cells (CD3, CD4), nTregs (CD4, FOXP3), CD4+ naïve cells (CD4, CD45RA), exhausted cells (CD3, PD-1), and central memory T cells (CD45RO)." (PMID 36032097, 2022). "Notably, most of the relevant actors involved in the anti-tumour immune response have been described to express DRD3, including CD8+ T-cells, effector CD4+ T-cells, Treg, macrophages, NK cells, B-cells, and DCs." (PMID 36428964, 2022). "In addition, treatment with XRT+αCTLA4+αPD1 resulted in a significant increase in the percentage of CD4+ T cells (as well as a trend to Treg increase) and a concomitant decrease in the percentage of CD8+ T cells and NK cells within the secondary tumor." (PMID 36405757, 2022). "Such experiments are important to distinguish the true function of CD4 Tfh and B cells in HNSCC, since they may be a secondary feature of tumor immune biology." (PMID 35937775, 2022). "In agreement, depletion of B and CD8+ cells, but not CD4+ cells, enhanced the metastatic potential of ΔS tumor cells to levels observed for ΔL tumors." (PMID 36344707, 2022). "RFA increases TIL number and CD8+/CD4+ ratio in TMERFA significantly increases the Teff/Treg ratio.RFA upregulates PD‐L1 expression in tumor cells, even for distant mock metastases without ablation.HIT enhances the expression of IFN‐γ and TNF‐α." (PMID 35908281, 2022). "We found that CKAP2 expression presented weak but significant positive correlations with infiltrating levels of B cells, CD8+ T cells, CD4+ T cells, macrophages, neutrophils, and dendritic cells, indicating a potential function of CKAP2 in regulating the tumor immunology of BC." (PMID 35954424, 2022). "We demonstrated that CD4+ and CD8+ T cells acquire their exhausted features at the early stage of oral carcinogenesis prior to tumor establishment, which could in turn accelerate the development of oral carcinogenesis." (PMID 35179267, 2022). "HIV-infected CRC patients had similar tumor-infiltrating lymphocytes (CD4 and CD8 T cells) compared to non-HIV-infected controls and substantially similar PD-1 expression on TILs and PD-L1 expression on tumors." (PMID 35311077, 2022). "In this context, genetically modified DCs, designed to express, process, and present a tumor antigen on MHC-II molecules, might represent an innovative strategy in immunotherapy to increase CD4+ T cell activation." (PMID 36139357, 2022). "Compared with CD4+ helper T cells, the infiltration of CD8+ T cells in tumor was relatively higher." (PMID 35662746, 2022). "Moreover, compared with the DIM-treated group, the percentage of CD4+ and CD8+ T cells was found to decrease in spleen, blood and tumor tissue from MDSCs adoptive transfer group." (PMID 35773674, 2022). "Interestingly, plasma IFN-γ secreting from URB also can polarize the macrophages in murine spleen, enhancing their antigen presenting effects and producing more CD4+ and CD8+ T cells to inhibit the tumor metastasis and distant tumor growth." (PMID 35918309, 2022). "Both CD8+ and CD4+ T cells play important effector roles in anti-tumor immunity, and investigators interested in querying antigen-specific responses in pools containing both CD8+ and CD4+ T cells should consider inclusion of Signal F and DC-LAMP in mRNA expression constructs." (PMID 35148673, 2022). "As a control, we performed a parallel experiment with naïve CD4+ T cells and PB Tregs from age-, sex-, tumor-, and ICI-matched patients in the no-irAE group." (PMID 35413951, 2022). "By assessing the infiltration of major cytotoxic immune cells, our data revealed no impact on the infiltration of CD8, CD4 and Tregs into the tumor microenvironment of TH-MYCN tumors following treatment with JQ1." (PMID 36139358, 2022).
tumor (continued). "CD4+ and CD8+ T cells play different roles in the tumor microenvironment (TME)." (PMID 35309293, 2022). "In addition, this CD4+ T cell subset also produces cytotoxic cytokines such as IFN-γ and TNF and therefore directly targets tumor cells." (PMID 35574343, 2022). "The tumor core analysis demonstrated an immune desert with few immune cell infiltration, mainly CXCR3+ CD4+ cells, suggesting a new role for CXCR3 that grants access to CD4+ cells." (PMID 36050391, 2022). "Tumor infiltrating effector T cells, which can recognize tumor associated antigens (TAA) and selectively eliminate cancer cells together with NK cells, are in a critical equilibrium with immunosuppressive CD4+CD25+Foxp3+ Tregs, providing one known mechanism determining tumor control vs. progression." (PMID 35615083, 2022). "A moderate correlation was observed between frequencies of FoxP3+ Tregs and CD4+LAG-3+ T cells in PBMCs of CRC patients, and it was found to be stronger in advanced tumor stages compared to early stages (r = −0.022, p = 0.945 [early]; r = 0.488, p = 0.039 [advanced])." (PMID 36146549, 2022). "IHC showed more CD4+ and CD8+ T cells infiltration in tumor tissue." (PMID 36245000, 2022). "Nevertheless, without CD8+ T cells targeting the same antigen, CD4+ T cells have been proven to protect against tumor growth." (PMID 36263174, 2022). "T cells CD4 memory resting, which were the main components of PRAD, were significantly lower than subgroup 1 and subgroup 3, which was consistent with tumor purity." (PMID 35785167, 2022). "Further analysis showed that there is a negative correlation between RNF183 expression and tumor purity, infiltrating levels of CD4+ T cells, neutrophils, and dendritic cells." (PMID 35163161, 2022). "CD4+ T cell immunity against OVA-positive tumor cells did not affect the nearby normal mammary glands." (PMID 35657353, 2022). "Our findings revealed that METTL24 was more likely to be a tumor suppressor gene in KIRC tumorigenesis, and the findings suggested that METTL24’s effects on CD4+ and CD8+ T cell infiltration might be involved in its functions in tumors." (PMID 36311770, 2022). "Endogenous CD4 + T cells can enhance TME immune tolerance and promote tumor growth." (PMID 35879796, 2022). "αPD-1 significantly improved polyfunctional T cells in both CD4+ and CD8+ subsets in aged mice, which could help explain its efficacy in them against B16F10 tumor growth, although many other factors are likely also involved." (PMID 36876140, 2022). "Therefore, this nanoplatform dramatically reversed CD206+F4/80+CD11b+ TAMs to CD86+F4/80+CD11b+ M1 phenotype, decreased immunosuppressive FOXP3+CD4+CD25+ Treg cells, and increased anti‐tumor IFN‐γ+CD8+ T cells in B16F10 and 4T1 tumor‐bearing mice." (PMID 37323705, 2022). "The presence of CD3+, CD4+ and CD8+ immune cell populations was detected within the tumor." (PMID 35804865, 2022). "In this evaluation, we could also verify that the tumor size is significantly correlated with the presence of Th17/Th1 (CD4+ CCR6+ CCR5+ CXCR3−) and Th17 cells (CD4+ CCR6+ CCR5− CXCR3−) cells in the TME." (PMID 36551555, 2022). "CD3 and CD20 were negative; however, one showed positivity of tumor cells for the T-cell marker, CD4." (PMID 36614926, 2022). "In addition to increasing the tumor antigen presentation, ACB1801 induces a deep modification of the immune landscape of B16-F10 tumors characterized by an increase of NK, CD4, and CD8 T cells and decrease of Tregs infiltration in the tumor microenvironment." (PMID 36458012, 2022). "In addition, CXCL16 can recruit CD4+ T cells and NKT cells to kill these senescent aging tumor cells." (PMID 35915657, 2022). "The results also suggested that ANLN expression was highly correlated with immune infiltration in LIHC; indeed, in LIHC, ANLN expression was positively correlated with tumor purity, CD8+ T cells, CD4+ T cells, B cells, neutrophils, and macrophages and negatively correlated with NK cells (P < 0.05)." (PMID 35568883, 2022).
tumor (continued). "However, our study revealed a decreased prevalence of both CD4+ and CD8+ immunoregulatory T (Treg) cells in the circulation of advanced tumor stages." (PMID 36428793, 2022). "In mouse models, CCL21 treatment led to higher infiltration of DCs CD4+ and CD8+ in tumor." (PMID 34439191, 2021). "Treg cells from CD4+ CD25– T cells are induced and increase in number in cancer patients, and in experimental tumor models, the application of monoclonal antibodies (mAbs) to deplete these cells is associated with increased immunity against tumor antigens and improved survival rates." (PMID 34113610, 2021). "In particular, Oxa(IV)@ZnPc@M mediated chemo-photodynamic therapy combined with anti-PD-L1 can effectively eliminate the primary and bone metastatic tumors, and boost the tumor-infiltration of cytotoxic CD8+ and CD4+ T cells with little systemic toxicity in two breast cancer models." (PMID 34262026, 2021). "A lack of CD4 tumor-specific epitopes led to induction of robust amounts of tumor-specific CD8 T cells that were incapable of tumor surveillance." (PMID 34209393, 2021). "Anti-CD4 and anti-CD8 IHC stainings showed that although YM101 had a modest effect on the number of CD4+ and CD8+ T cells in the peritumoral stroma, YM101 markedly increased the quantity of T cells in tumor center." (PMID 33593403, 2021). "Analysis of the proportion of immune cells in tumor tissue of two groups divided by the TMEscore showed that the proportions of M1 macrophages, CD8+ T cells, and activated CD4+ memory T cells were increased in the high TMEscore group, as well as the IFN-gamma related genes." (PMID 34712666, 2021). "A previous study presented that CD4+ T cells and CD8+ T cells were generally believed to control cancer outcome, while macrophages and neutrophils produce various factors that induce inflammation and stimulus tumor progression." (PMID 34497675, 2021). "The current results of this investigation envisage the potential effect of the new immunotherapy in stimulating the activity of CD4+ and CD8+ antitumor specific T lymphocytes either in the tumor-infiltrating microenvironment and at distant sites in the periphery." (PMID 34539667, 2021). "As previously seen for macrophages (F4/80), also CD4 T cells and CD11c myeloid/dendritic cells were present inside the tumor nests and the stroma with no apparent difference between genotypes." (PMID 33988305, 2021). "Next, we determined that cleaved caspase levels in CD4+ Foxp3−, CD8+ T cells, tumor cells, and other cell populations were equivalent, suggesting that Tregs were not dependent upon TRAIL-mediated cytotoxicity in the TME of BALB/c mice, possibly because of low DR5 expression in the TME." (PMID 33483333, 2021). "The increase in the ratio of CD8:CD4, CD25 is characteristic of increased anti-tumor CD8 T cells." (PMID 34638488, 2021). "This upregulation of antiapoptotic genes could lead to increase in levels of CD4+ TILs and shift the balance between Th cells and CTLs in the TME, which favors tumor progression." (PMID 33916009, 2021). "While most tumor immunotherapies involve CD8+ T cells, the data we present here are also consistent with a reliance upon CD4+ T cells, either for their own cytokine production or for their ability to help mount a protective B cell response; these possibilities cannot be ruled out." (PMID 33562450, 2021). "There are also contrasting prognostic effects of the Foxp3/CD4 ratio in CGC and NCGC, which suggests that location may be an important factor for tumor progression." (PMID 34926251, 2021). "The sole PD-1 blockade did not leave effect on the priming of CTL or infiltration of tumor, thus these findings suggested that it co-functioned with the help of CD4+ T cell by reducing suppression of CTL in the tumors." (PMID 34267616, 2021).